FREM2 (FRAS1 related extracellular matrix 2)
Diseases named in the same sentence as FREM2 in open-access papers (continued):
Sharing a sentence is not in itself a finding about the gene and the disease.
glioblastoma (continued). "When the “old” classification was used, the expression of CRNDE, FREM2, and SPRY genes allowed the diagnosis of “glioblastoma, grade IV” to be differentiated from the lower grade gliomas (astrocytomas, oligoastrocytomas, and oligodendrogliomas)." (PMID 36613601, 2022). "In this study, we explored the roles of the FREM2 and SPRY1 genes and their proteins in glioblastoma pathology using human tissue samples." (PMID 31357584, 2019). "As such, for the first time, we deeply examined the relationships between both the FREM2 and SPRY1 genes and their proteins in glioblastoma." (PMID 31357584, 2019). "The study was based on previous data where we presented differential expression levels of the FREM2 and SPRY1 genes and their proteins in different glioblastoma cells, compared to astrocytes." (PMID 31357584, 2019). "We discovered higher FREM2 and SPRY1 gene expression levels in glioblastomas compared to lower grade gliomas and reference samples." (PMID 31357584, 2019). "In addition, FREM2 was over-expressed at the protein level in glioblastoma stem-like cells in comparison to mature GBM cells as well as neural stem cells." (PMID 29734672, 2018). "In addition, the FREM2 and SPRY1 proteins show specific localization on the surface of glioblastoma cells." (PMID 31357584, 2019). "We also observed differences in FREM2 expression between IDH-mutant and IDH-WT glioblastomas." (PMID 31357584, 2019). "In our previous study, we carried out a meta-analysis of the data from publicly available repositories, whereby we selected two genes that show selectivity towards glioblastoma: those for FRAS1-related extracellular matrix protein 2, FREM2, and sprouty RTK signaling antagonist 1, SPRY1." (PMID 31357584, 2019). "Finally, we performed in-silico analysis using TCGA database, which indicated increased FREM2 and SPRY1 gene expression in glioblastomas compared to lower grade gliomas and reference samples." (PMID 31357584, 2019). "We showed increased FREM2 gene expression and FREM2 protein expression levels in glioblastoma cells, compared to nonmalignant astrocytes." (PMID 31357584, 2019). "This validation revealed that the expression of FREM2—but not SPRY1—is higher in glioblastoma cell lines when compared to non-malignant astrocytes." (PMID 29734672, 2018). "Recently, it has also been shown that observing changes in the FREM2 signaling pathway, rather than only the FREM2 expression level, represents a more reliable prognostic glioblastoma biomarker that is comparable to the already established isocitrate dehydrogenase (IDH) biomarker." (PMID 39982223, 2025). "We used the UALCAN database to analyze the expression levels of FREM2 in pan-cancer and found that FREM2 was mainly highly expressed in COAD, glioblastoma multiforme (GBM), stomach adenocarcinoma (STAD), and uterine corpus endometrial carcinoma (UCEC)." (PMID 35252356, 2022). "Finally here, using multivariate analysis we showed a positive correlation between FREM2 and survival of patients with IDH-WT glioblastomas, and a negative correlation between FREM2 and survival of patients with IDH-WT lower grade gliomas." (PMID 31357584, 2019). "Previously, we identified FREM2 and SPRY1 as genes with differential expression in glioblastoma cell lines compared to nonmalignant astrocytes." (PMID 31357584, 2019).
glioma (8 papers, 2019 to 2023). A benign or malignant brain and spinal cord tumor that arises from glial cells (astrocytes, oligodendrocytes, ependymal cells). "FREM2, which was found to be amplified in young patients in this study, was also reported to be associated with unfavorable outcomes in glioma patients." (PMID 36685821, 2022). "We report here a new reconstructed FREM2 molecular pathway, which activation is strongly associated with unfavorable prognosis in glioma patients." (PMID 34439271, 2021). "FREM2 is associated with mesenchymal differentiation in gliosarcoma because it was strongly overexpressed in mesenchymal compared to glial tumor areas." (PMID 34439271, 2021). "Additionally, loss of FREM2 function is an important cause of blood-related kidneys, and FREM2 has been suggested to be a candidate prognostic marker in glioma." (PMID 35252356, 2022). "In addition, a higher FREM2 pathway activation level was associated with lower progression-free survival in gliomas." (PMID 36613601, 2022). "Expression of SPRY1 gene, another potential glioma biomarker that showed comparable characteristics to FREM2 in the previous study, was also associated with survival and showed a similar pattern to FREM2 expression." (PMID 34439271, 2021). "In addition, we observed that low FREM2 expression was associated with progression of IDH-mutant low-grade glioma patients." (PMID 31357584, 2019). "One such algorithmically constructed pathway centered at gene FREM2 emerged as a promising predictor of tumor grade and survival in human gliomas, strongly exceeding the biomarker performance of the FREM2 gene itself." (PMID 37755705, 2023). "Recently, it has been found that FREM2 is highly expressed in gliomas and that patients with high expression levels of FREM2 show a better prognosis." (PMID 35252356, 2022). "We have established that an algorithmically reconstructed molecular pathway centered around FREM2 predicts negative associations with survival and molecular and histological subtypes of gliomas considerably more strongly than the paternal gene FREM2 alone." (PMID 35806337, 2022). "Our data show lower FREM2 gene expression for patients with IDH-WT gliomas whose disease progressed after temozolomide treatment." (PMID 31357584, 2019). "Much better results were obtained for the activation of FREM2 pathway, as PALs returned relatively higher AUC values and allowed all major types of gliomas to be distinguished from each other, with the only exception being low- and high-grade “astrocytomas, IDH-mutant”." (PMID 36613601, 2022). "In addition, increased FREM2 gene expression was demonstrated in gliomas compared to the normal glia, and in GBM compared in LGG." (PMID 34439271, 2021). "In addition, there was an association between decreased FREM2 gene expression and bad outcome in IDH-mutant lower grade gliomas." (PMID 31357584, 2019). "We observed that FREM2 protein expression levels increased with glioma grade progression." (PMID 31357584, 2019). "Indeed, according to this in-silico analysis of TCGA data, FREM2 expression is lower in tissue samples from patients with low grade IDH-mutant gliomas that progressed after temozolomide treatment than in patients with stable or responsive disease." (PMID 31357584, 2019). "Thus, we propose that these components of the FREM2 pathway are important actors of glioma pathogenesis and could be regarded as the possible new targets for next-generation molecular therapeutics." (PMID 34439271, 2021). "We also reconstructed the FREM2 molecular pathway using the human interactome model and found that it had a significantly better performance as the OS and PFS biomarker of gliomas." (PMID 34439271, 2021). "We validated the FREM2 and SPRY1 genes and their proteins in glioma tissue samples from different grades with respect to different human cancers and reference samples." (PMID 31357584, 2019).
glioma (continued). "Thus, we performed a total of 48 comparisons for each possible biomarker under investigation (FREM2 expression, PAL1-3) on different sets of glioma samples." (PMID 34439271, 2021). "They further investigated different areas of the analyzed gliosarcomas, and found amplification of the FREM2 gene and overexpression of the FREM2 protein in the mesenchymal areas, and not in the glial tumor areas, of the gliosarcomas." (PMID 31357584, 2019). "The decreased proteins include proteins with known functions for glioma stemness and migration/invasion like CD9 (Gos, ATO/Gos), Ephrin receptor A2 (EPHA2; Gos, GANT/Gos) and mesenchymal (i.e., more aggressive) differentiation like FRAS1 related extracellular matrix protein 2 (FREM2; ATO/Gos)." (PMID 30871073, 2019). "At the transcriptomic level, both FREM2 and SPRY1 show increased expression in tissue samples of different glioma grades compared to nonmalignant brain tissue." (PMID 31357584, 2019). "Using qPCR, we examined the patterns of the gene expression levels of FREM2 and SPRY1 in glioma tissue samples of different WHO grades, as well as in nonmalignant brain tissue samples." (PMID 31357584, 2019). "To evaluate potential use of our previous findings for clinical purposes, we performed a pilot study where we examined the expression of FREM2 and SPRY1 at the proteomic and transcriptomic levels in different grades of gliomas and nonmalignant brain-tissue samples." (PMID 31357584, 2019).
cryptophthalmos (5 papers, 2010 to 2025). "Here, we used untargeted metabolomics analysis in conjunction with RNA-seq, to examine the contribution of metabolites and metabolism-related genes in modulating cryptophthalmos susceptibility in Frem2 mutant fetal mice." (PMID 33490088, 2020). "Mutations in the FREM2 gene result in reduced epithelial-mesenchymal coupling and transient embryonic epidermal blistering, leading to the development of cryptophthalmos." (PMID 33490088, 2020). "We suggest that the metabolites established before birth may have an impact on cryptophthalmos susceptibility in Frem2 mutant mice." (PMID 33490088, 2020). "Metabolomic and transcriptomic signatures provide a map of metabolism in the Frem2 mutant mouse model of cryptophthalmos." (PMID 33490088, 2020). "Overall, we demonstrate that changes in metabolome composition may have contributed to the development of the cryptophthalmos phenotype in Frem2 mutant mice." (PMID 33490088, 2020). "Our findings suggest that the metabolomic signature established before birth may play a role in mediating cryptophthalmos in Frem2 mutant mice, which may have important implications for the pathogenesis of cryptophthalmos." (PMID 33490088, 2020).
colorectal cancer (4 papers, 2022 to 2025). A primary or metastatic malignant neoplasm that affects the colon or rectum. "In the same way as in previous reports, FREM2 expression was increased in colorectal cancer foci by immunohistochemistry study and FREM2 mutation was related to poor oncological outcomes." (PMID 38062443, 2023). "For example, FREM2 is associated with immune checkpoints and may serve as a prognostic marker in colorectal cancer patients." (PMID 41426592, 2025). "According to existing investigations, FREM2 is associated with immune checkpoints, and its variants may serve as prognostic markers in colorectal cancer patients." (PMID 41426592, 2025). "Furthermore, FREM2 mutations may be potential prognostic markers in colorectal cancer, a disease modified by MUC3A, a gene that was mutated in our five patients with HSD." (PMID 35886052, 2022).
renal agenesis (3 papers, 2013 to 2022). Renal agenesis (RA) is a form of renal tract malformation characterized by the complete absence of development of one or both kidneys (unilateral RA or bilateral RA respectively), accompanied by absent ureter(s). "We also observed kidney phenotypes comprising bilateral and unilateral renal agenesis and/or hypoplasia (Frem2 and 1G, Plxnd1)." (PMID 27002738, 2016). "Apoptosis of cells in the metanephric mesenchyme, leading to renal agenesis, is also seen in mice that lack the cytosolic adapter protein GRIP1, which plays a critical role in trafficking FRAS1 and FREM2 to the plasma membrane." (PMID 23536828, 2013). "Given the known interactions between these proteins, it is not surprising that FREM1-, FRAS1-, FREM2- and GRIP1-deficient mice have overlapping patterns of defects that include cryptophthalmos and syndactyly–which are likely to be secondary effects of blister formation–and renal agenesis." (PMID 23536828, 2013).
breast carcinoma (2 papers, 2020 to 2022). "FREM2 has been identified as a target gene of TFAP2C (transcription factor AP-2 gamma) in hormone-responsive breast cancer cells." (PMID 32156290, 2020).
congenital diaphragmatic hernia (2 papers, 2013 to 2020). A posterolateral defect of the diaphragm that allows passage of abdominal viscera into the thorax, leading to respiratory insufficiency and persistent pulmonary hypertension with high mortality. "Similarly, recessive mutations in Frem1 have been shown to cause congenital diaphragmatic hernia (CDH) which has not been documented in mice with Fras1, Frem2 or Grip1 mutations." (PMID 23536828, 2013).
Frasier syndrome (2 papers, 2016 to 2021). Frasier syndrome is characterized by the association of male pseudohermaphrodism and glomerular nephropathy. "However, the phenotype of the patient did not fit the Smith–Lemli–Opitz syndrome (MIM 270400) or 46,XY Frasier Syndrome (MIM 136680), which are associated with DHCR7 and FREM2, respectively." (PMID 34943163, 2021).
ovarian carcinoma (2 papers, 2021 to 2023). A malignant neoplasm originating from the surface ovarian epithelium. "In ovarian cancer, the differential expression of FREM2 has been reported in a few studies." (PMID 34149794, 2021).
renal carcinoma (2 papers, 2022 to 2024). A carcinoma arising from the epithelium of the renal parenchyma or the renal pelvis. "The results of immunohistochemical analysis indicate that the expression levels of COL9A3, GPC4, and ITGA6 in renal cancer tissue are higher than those in normal tissue, whereas the expression levels of FREM2, ITGA9, and P3HI are lower than in normal tissue." (PMID 38365923, 2024).
brain tumor (1 paper, 2019). "We took FREM2 and SPRY1 gene expression, age, sex, and histological type of brain tumor as covariates." (PMID 31357584, 2019).
colon adenocarcinoma (1 paper, 2022). "We performed somatic mutation analysis using data sets from The Cancer Genome Atlas and International Cancer Genome Consortium, and identified that FREM2 had the highest mutation frequency in patients with colon adenocarcinoma (COAD)." (PMID 35252356, 2022).
cryptorchidism (1 paper, 2017). The failure of one or both testes of a male fetus to descend from the abdomen into the scrotum during the late part of pregnancy. "Besides, MAF of SNPs in SMAD4 and FREM2 (rs2496423) is lower than 1%, suggesting that these rare variants is possibly pathogenic for CAKUT accompanied with by cryptorchidism." (PMID 29197384, 2017).
cyst (1 paper, 2016). A sac-like closed membranous structure that may be empty or contain fluid or amorphous material. "Although Frem2 haploinsufficiency does not overtly affect nephrogenesis in mice, expression of Frem2 in adult kidneys correlated with cyst formation in homozygous mutant mice, indicating that the gene is required for maintaining the differentiated state of renal epithelia." (PMID 27736906, 2016).
hydronephrosis (1 paper, 2024). Collection of urine in the renal pelvis that results in dilatation of the renal pelvis and calyces. "Some of the CAKUT cases with associated malformations did reveal a pathogenic variant in WES (unilateral renal agenesis Hypomethylation C2; horseshoe kidney KMT2A; hydronephrosis FREM2, KANSL1; LUTO CHD7; renal hypoplasia GREBIL, POGZ)." (PMID 37535131, 2024).
kidney cancer (1 paper, 2022). Primary or metastatic malignant neoplasm involving the kidney. "We obtained immunohistochemical data on FREM2 expression level in kidney cancer from the Human Protein Atlas database, We further verified the expression level of FREM2 in human kidney cancer and normal tissues by qRT-PCR." (PMID 36439501, 2022).
kidney tumor (1 paper, 2022). "In addition, we verified the FREM2 expression level in kidney cells by qRT-PCR, and the FREM2 expression level was higher in HK-2 normal kidney cells and lower in kidney tumor cells (ACHN and CAKI cell lines), which was basically consistent with the human tissue verification results." (PMID 36439501, 2022).
leukaemia (1 paper, 2018). "In view of the possible association with T-ALL, and the emerging role of the micro-environment/extracellular matrix in leukaemia and cancer, we included FREM2 mutations in our single-cell studies." (PMID 29556024, 2018).
liver cancer (1 paper, 2022). An epithelial or non-epithelial malignant neoplasm that arises from the liver. "As liver cancer is considered an immunogenic tumor, the relationship between the expression of DOCK2, SCTR, TANC1, ALKBH7, FREM2, and GNG4 and the levels of immune cells and stromal cells was assessed." (PMID 35620462, 2022).
malignant glioma (1 paper, 2021). A grade III or grade IV glioma arising from the central nervous system. "Instead, further investigation of the FREM2 pathway can help to find and validate additional molecular targets that could be affected in a combinational therapy of malignant gliomas." (PMID 34439271, 2021).
microphthalmia (1 paper, 2020). Congenital or developmental anomaly in which the eyeballs are abnormally small. "H&E staining confirmed microphthalmia and showed dysplastic eye structures in the Frem2 mutant embryo." (PMID 33490088, 2020). "Our results confirmed that the phenotype of Frem2 mutant embryonic mice shows consistent results with that of the adult mice characterized by abnormal eyelids, microphthalmia, and developmental defects in the anterior segment." (PMID 33490088, 2020).
myelomeningocele (1 paper, 2022). Myelomeningocele is the most severe form of spina bifida. "Similarly, ultra-rare deleterious variants in the extracellular matrix genes FRAS1-related extracellular matrix 2 (FREM2) and perlecan (HSPG2) were found to be associated with myelomeningocele in a cohort of North American individuals." (PMID 34842271, 2022).
Nephropathy (1 paper, 2016). A nonspecific term referring to disease or damage of the kidneys. "Three genes (Frem2, Foxo1 and Setd7) have been implicated in nephropathy." (PMID 27736906, 2016).
prostate adenocarcinoma (1 paper, 2022). "In prostate adenocarcinoma, FREM2 was found to be one of the most recurrently mutated genes." (PMID 35620462, 2022).
ZIKV infection (1 paper, 2023). "Knockdown of FREM2 in NPCs resulted in reduced expression of pluripotency marker Sox2 and increased expression of neuronal lineage marker βIII-Tubulin, mimicking human ZIKV infection, and potentially contributing to Zika syndrome." (PMID 36979701, 2023). "Notably, ZIKV infection of NPCs particularly impacts the expression of FREM2 (FRAS1-related extracellular matrix protein 2), which is a critical neurodevelopmental gene." (PMID 36979701, 2023).